LEP (leptin)
Diseases named in the same sentence as LEP in open-access papers (continued):
Sharing a sentence is not in itself a finding about the gene and the disease.
Obesity (continued). "There may also be an interesting connection with leptin: increased leptin secretion from adipose tissue and elevated circulating leptin are seen in obesity, and indeed an association between leptin and norepinephrine exists, for instance during a glucose tolerance test." (PMID 36074318, 2022). "A common LEP G2548A polymorphism (rs7799039) consisting of a G→A transition at nucleotide −2548 upstream of the ATG start codon in the 5′ promoter was also associated with obesity or body weight gain in various cases, whereas other reports failed to prove such an association." (PMID 35563103, 2022). "This systemic and adipose tissue inflammation, which causes increases in the production of leptin and pro-inflammatory cytokines, is one of the pathways that could illustrate the connection between obesity and the progression of NCDs, with the cause of chronic low-grade inflammation." (PMID 36151575, 2022). "In addition, mice lacking ROCK1 in pro-opiomelanocortin and agouti-related protein neurons, which are mediators of leptin action, displayed obesity and impaired leptin sensitivity associated with increased food intake, reduced energy expenditure and locomotor activity." (PMID 35769086, 2022). "Increased adherence to EDII yielded an increase of 16.73 mg/l in leptin level (β= 16.73, 95% CI= 1.56, 39.3, P= 0.04) and 0.55 in leptin resistance (β=0.55, 95% CI=0.00, 1.30, P= 0.06) in model 2, which was adjusted for, economic status, education level, age of starting obesity, weight loss history." (PMID 36151575, 2022). "Moreover, previous studies showed that habitually short sleep duration was significantly associated with reduced leptin and elevated ghrelin levels, increased caloric intake and unhealthy food choices, any of which could promote the development of obesity." (PMID 36119748, 2022). "Therefore, antipsychotic-induced ER stress may also cause leptin and insulin resistance, and these effects may worsen obesity and inflammation development during antipsychotic treatment." (PMID 36188456, 2022). "This raised the possibility that obesity may be associated with a form of “leptin resistance”." (PMID 34680059, 2021). "Therefore, a strong possibility of neutralizing the circulatory leptin could control the hyper cytokine responses that are linked to obesity in COVID-19 patients." (PMID 34220807, 2021). "Moreover, in the validation cohort, although leptin levels positively correlated with BMI, they were higher in NAFL and NASH compared with both non-obese and obese controls, suggesting that the association between NAFLD and leptin is more robust than the effect of obesity on leptin levels." (PMID 34249975, 2021). "We hypothesize that beneficial effects of maternal exercise on maternal and fetal metabolism could partly be mediated through regulation of fat mass and adipokine levels, perhaps predominantly in women with obesity who exhibit excess adiposity and underlying hyperleptinemia and leptin resistance." (PMID 34131242, 2021). "Similarly, endothelial dysfunction associated with obesity may impair the vasodilative effect of leptin and also contribute to hypertension." (PMID 34412646, 2021). "The adipocyte secretion-associated alteration in obesity, including the changes in the ratio of leptin to adiponectin, the expression levels of pro-inflammatory cytokines, IGFs, and estrogen, may be the mechanisms potentially leading to BC immunotherapy resistance." (PMID 34350120, 2021). "Obesity during adolescence has been associated with an increased risk of developing MS due to its correlation with both a chronic inflammation status (especially through the production of cytokines, such as leptin, which influences immune response), and with low levels of vitamin D." (PMID 33918133, 2021).
Obesity (continued). "While it is still inconclusive whether metabolic conditions of mothers (such as obesity) upregulate or downregulate the placental production of leptin, DM and pre-pregnancy overweight likely cause an increase in cord serum leptin levels, thereby leading to altered neurodevelopment in offspring." (PMID 35185642, 2021). "Obesity causes changes in the circulating levels of adiponectin, leptin, and resistin by adipocytes, which can act as a regulatory link between the endocrine system and the immune system, playing a role in the relationship between obesity, asthma, and diabetes." (PMID 33520042, 2021). "Therefore, the effects of leptin on obesity-associated inflammation might be dose-dependent, and the management of obesity-associated diseases by using leptin as a potential therapeutic target requires careful consideration." (PMID 34421909, 2021). "Previous studies showed that insulin resistance/hyperinsulinemia, abnormal endogenous estrogen signaling, inflammatory cytokines, and adipocytokines (IL-6, TNF-α, adiponectin, visfatin, and leptin) may be the main mechanisms behind obesity that is associated with EC." (PMID 34975754, 2021). "Mutation of the leptin gene may results indevelopment of obesity and type 2 DM." (PMID 35539887, 2021). "Moreover, dysfunctions in host immunity associated with obesity, including altered T cell responses, increased secretion of leptin, and interferon γ may explain the increased rates of upper respiratory infections in obese children." (PMID 33919665, 2021). "Adiponectin and leptin are involved in the maintenance of glucose, lipid and energy homeostasis; adiponectin is secreted exclusively from adipose tissue and is inversely associated with obesity, thus increasing adipocyte lipid storage/adipogenesis and reducing lipid accumulation." (PMID 34451825, 2021). "Similarly, downstream mutations in the leptin cascade can lead to obesity." (PMID 33572982, 2021). "Notably, obesity-associated leptin was found to induce STAT3 signaling in CD8+ TILs." (PMID 34421889, 2021). "Moreover, high leptin and resistin levels impaired the therapeutic effects of dacarbazine in melanoma and their reduction improved the drug efficacy, which supports the importance and influence of leptin in obesity-associated conditions." (PMID 34202969, 2021). "Furthermore, the control of mucus, including the target of IL-33 and leptin, may be a therapeutic strategy for obesity-associated asthma." (PMID 34074279, 2021). "Therefore, we speculate that the accelerated growth in the children with CLD at T0 may be linked with their obesity by leptin-independent mechanisms, such as hyperinsulinism." (PMID 34002033, 2021). "Leptin (LEP) may be associated with obesity and breast cancer prognosis." (PMID 34414945, 2021). "Furthermore, obesity and leptin resistance are risk factors for AD." (PMID 34827650, 2021). "Herein we review the available evidence on the various aspects of the association between obesity and viral infections and the current understanding of the possible mechanisms underlying this susceptibility to worse outcomes, with particular focus on the role of leptin." (PMID 33804765, 2021). "Furthermore, leptin (which is increased in both migraine and obesity), is associated with cortical spreading depression, suggesting that increases in leptin levels in obesity may induce chronic migraine." (PMID 34177788, 2021). "In addition, functional LepR was specifically down-regulated in the hypothalamus of infected obese mice, suggesting that CDV infection in the brain induced leptin resistance in the hypothalamus, which led to obesity, thereby increasing the risk of MetS-associated cognitive impairment." (PMID 34795562, 2021).
Obesity (continued). "At 20 years the study suggested that low fat intake in early childhood increased the susceptibility to the development of obesity and leptin resistance in adulthood, and that early programming of leptin resistance might be one way in which nutrition in infancy could affect adiposity development." (PMID 34579140, 2021). "Therefore, high circulating leptin might involve dysregulation of proinflammatory cytokine in obesity, which is the leading cause of high morbidity and mortality in patients with SARS-CoV-2 infection." (PMID 34220807, 2021). "Consequently, SARS-CoV-2 MA can be applied to the existing mouse models to better understand the impact of COVID-19 on obesity, such as genetically obese mouse models, including leptin-deficient (ob/ob) and leptin-receptor-deficient (db/db), as well as high-fat diet-induced-obese (DIO) mouse model." (PMID 34204163, 2021). "If leptin levels in LEP wt/- are confirmed to be low in relation to their body fat, LEP heterozygosity may represent a condition of relative leptin deficiency, implying possible therapeutic options in LEP heterozygotes showing overweight or obesity." (PMID 34448070, 2021). "In the state of negative energy balance, the resulting rapid decrease in circulating leptin concentration is sensed by the CNS and, in response, drives hunger, suppresses energy expenditure, and reduces reproductive competence; despite potentially underlying obesity." (PMID 34955895, 2021). "For instance, obesity induced by a high-fat diet or the mutation of the leptin gene or receptor is associated with increased circulating resistin concentrations, whereas resistin expression was downregulated in rodent models with diet-induced obesity and suppressed by free fatty acids." (PMID 34579022, 2021). "Obesity is associated with an increased basal lipolysis, which might be caused by an impaired sensitivity of adipocytes to insulin signaling, overexpression of the leptin gene in adipocytes, and increased circulating levels of leptin." (PMID 33498674, 2021). "Notably, whether hypothalamic inflammation and associated ER stress and autophagy disorders, which have been extensively linked with diet-induced obesity, are causative or a consequence of leptin resistance is yet to be determined." (PMID 34613819, 2021). "Thus, the causal relationship among estimated salt intake, leptin levels, and obesity was unclear." (PMID 34578892, 2021). "Thus, in obesity and MetS, hypothalamic inflammation may cause resistance to the anorexigenic hormones leptin and insulin, leading to the defective regulation of food intake and energy expenditure." (PMID 33557413, 2021). "In addition to its critical roles in the regulation of appetite and energy balance, a large body of evidence has indicated that leptin induces initial development and progression of various types of cancers, in particular obesity‐associated cancers, such as hepatic, colon, and breast cancer." (PMID 33226729, 2021). "Moreover, together with obesity-associated markers, serum reproductive hormones, lipids and leptin could also be included to evaluate male semen quality." (PMID 32993674, 2020). "In the opposite direction, chronic inflammatory states due to metabolic, autoimmune or infectious diseases may lead to leptin resistance at the central level, which is a known cause of obesity, therefore increasing leptin levels and further fueling the inflammation state." (PMID 32824322, 2020). "Interestingly, the modulation of hypothalamic SIRT1 has been implicated in the reduction of leptin resistance as a strategy for treating obesity, and the activation of SIRT1 by resveratrol improves peripheral and central leptin signaling and reverses leptin resistance caused by diet-induced obesity." (PMID 33202604, 2020).
Obesity (continued). "Moreover, obesity is associated with various metabolic disorders that can lead to an increase in cortisol, leptin and insulin levels, with consequent dysregulation of the HPA axis and insulin resistance which can further induce inflammation and worsen depression." (PMID 32545890, 2020). "In diet-induced obesity, leptin levels rise due to leptin resistance, a condition deriving from activation of an inflammatory pathway, and from systemic oxidative stress, and involved in skeletal muscle atrophy, a disorder also linked to obesity and inflammation." (PMID 32565792, 2020). "Obesity could be linked to the severity of COVID-19 via metabolic dysregulation, immune impairments and adiposopathy with altered adipokine levels, such as increased leptin and decreased adiponectin concentrations." (PMID 33327389, 2020). "Furthermore, genetic components such as hereditary deficiency and genetic variations including leptin gene mutations could also have a strong effect on the development of excess weight gain and obesity." (PMID 32164196, 2020). "Therefore, decreasing leptin and resistin concentrations may be considered a therapeutic target to reduce the inflammatory state associated with obesity." (PMID 33007981, 2020). "However, when obesity is induced with the introduction of either leptin or leptin receptor knockout mutations (lep-ob and lep-db, respectively), both male and female DBA mice develop a diabetes-like phenotype due to β-cell failure, indicating the presence of diabetes risk genes in the DBA genome." (PMID 33133152, 2020). "Finally, one of the peripheral functions of leptin is a regulatory role in the interplay between energy metabolism and the immune system, which is, in part, responsible for the inflammatory state associated to obesity." (PMID 32630697, 2020). "The association of leptin with amylin, a peptide hormone released with insulin by pancreatic beta cells which modulate glucose and energy homeostasis, showed enthusiastic results, predominantly mediated by decreased feeding and increased central leptin sensitivity in diet-induced obesity." (PMID 33192583, 2020). "The occurrence of this phenomenon may suggest that obesity is associated with leptin resistance." (PMID 32375231, 2020). "However, whether these variations in DNAm at the LEP gene locus are linked to future risk of obesity is still unknown." (PMID 31947745, 2020). "Another confirmation supporting our hypothesis was provided by a study from Friedman’s group demonstrating that leptin-deficient animals in which BWt was normalized by chronic low-level leptin infusion remained responsive to leptin, even when obesity was induced by a high-fat diet (HFD)." (PMID 32545900, 2020). "The leptin transgenic animals showed amelioration of high‐fat‐diet‐induced insulin resistance, whereas the leptin‐deficient ob/ob mice displayed obesity and insulin resistance with hyperinsulinaemia and hyperglycaemia, which might be reversed by exogenous leptin." (PMID 32395890, 2020). "Obese patients have higher leptin (pro-inflammatory adipokine) levels and lower adiponectin (anti-inflammatory adipokine) levels that induce immune response dysregulation and may lead to the pathogenesis of obesity-linked complications." (PMID 32916925, 2020). "Prepregnancy obesity and the serum leptin concentration are strong risk factors for pregnancy-associated gallbladder disease, although a human study showed that the serum leptin concentration might not be a better predictor of gallbladder disease than anthropometry." (PMID 33167521, 2020). "Interestingly, recent preclinical evidence has suggested that leptin resistance associated with obesity could be overcome which course with compensatory hyperleptinaemia." (PMID 32069871, 2020). "Thus, the use of drugs or specific bioactive food components with anti-inflammatory properties may help to reduce the inflammatory state associated with obesity and overcome leptin resistance, especially at the hypothalamus." (PMID 33312720, 2020).
Obesity (continued). "However, it is unclear whether AC protects or attenuates disease in obesity-related leptin-deficient (ob/ob) mice." (PMID 32164196, 2020). "Recent studies have proposed that leptin resistance may promote IR and cause the abnormal accumulation of lipids in the liver and cardiac and skeletal muscle, reducing fatty acid oxidation and consequently leading to obesity and MetS." (PMID 32517169, 2020). "Obesity-related HFpEF obtained in our experimental conditions was associated with a subclinical pro-inflammatory status highlighted by significantly increased IL-6 and leptin plasma levels, a trend for increased TNF-alpha and decreased adiponectin/leptin ratio, but without CRP modifications." (PMID 33142857, 2020). "Whether SST, which plays an essential role in obesity, is linked to leptin is not well understood." (PMID 32272767, 2020). "Thus, obesity is associated with metabolic abnormalities connected to an increase in circulating levels of insulin and impaired insulin action, as well as to the dysregulation of adipokine secretion (an increase in leptin and decrease in adiponectin levels)." (PMID 32947606, 2020). "Furthermore, obesity could lead to higher risk of thrombosis through the action of adipocytokines, such as leptin, adiponectin, and Resistin." (PMID 33113962, 2020). "In the 1990s, the discovery of leptin and leptin receptor genes and the leptin-driven melanocortin 4 signaling pathways prompted a sequence of genetic studies that uncovered rare mutations in single genes regulating appetite leading to early-onset extreme obesity." (PMID 32594318, 2020). "Some previous studies suggested that misalignment of circadian rhythm may decrease insulin sensitivity and leptin suppression, and time-restricted feeding is associated with a lower incidence of obesity compared with ad libitum diet with the same caloric intake in mice." (PMID 32948201, 2020). "Thus, the adiponectin to leptin ratio may be a useful means for estimating obesity-associated cardiometabolic risk." (PMID 33261143, 2020). "Moreover, liver function tests for biochemical abnormalities, a rise in leptin level, reduction in adiponectin level, changes in obesity-associated metabolizing enzyme activities, and oxidative damages were observed in liver and serum from the obese mice model." (PMID 33273564, 2020). "Moreover, the sympathetic nerve activation and subsequent sleep disturbance caused by increased leptin secretion after a meal may be involved in the excess risk of obesity from eating late-evening meals." (PMID 33081125, 2020). "In addition to differences in frequency, it was demonstrated that VAT-Tregs isolated from genetically promoted (leptin-deficient) or diet-induced (high fat chow) insulin-resistant mouse models of obesity have an altered transcriptional signature compared to lean mice." (PMID 32153577, 2020). "However, the relationship between FTO genotype and dietary intake seems to be very complex and many factors may have a role in this association such as the obesity, level of physical activity, serum leptin, and other dietary components." (PMID 32843047, 2020). "In fact, the prevalence of the obesity has been associated with prematurity, and it was reported that preterm children with higher adiposity and metabolic abnormalities, may have disproportionately higher values of fat mass and leptin." (PMID 32344627, 2020). "Thus, our findings are in accordance with the metabolic programming, in which altered leptin signaling in early life may predispose adult individuals to metabolic diseases, such as obesity." (PMID 30694175, 2019). "Because in patients with type 2 diabetes insulin therapy retained the ability to lower blood glucose despite hyperinsulinemia and insulin resistance, many hoped that, despite hyperleptinemia, leptin therapy might be effective in typical obesity and obesity-associated diabetes." (PMID 30357355, 2019).